APC (APC regulator of Wnt signaling pathway)
Diseases named in the same sentence as APC in open-access papers (continued):
Sharing a sentence is not in itself a finding about the gene and the disease.
colon carcinoma (continued). "APC inactivation has been found in more than 60% of colonic tumours and such inactivation is associated with up regulation of miR-135a/b in colonic epithelial cells." (PMID 22716183, 2012). "K-ras mutations are more common in colon cancer than in rectal cancer, the number of mutations in colon tumours is higher than in rectal tumours, and the mutational pattern restricted to the APC gene is more frequent in rectal than colon cancer." (PMID 21827717, 2011). "It is known that more than 80% of colorectal cancers have inactivating mutations in the adenomatous polyposis coli (APC), a tumor suppressor linked to the initiation and progression of colon cancer." (PMID 22249213, 2011). "These included mutations in KRAS and APC, two somatic genetic changes frequently observed in colon cancer." (PMID 21738606, 2011). "For example, allelic variation in APC (adenomatous polyposis coli) expression plays a role in predisposition to colon cancer." (PMID 21345208, 2011). "APC serves as a negative regulator of Wnt signaling, acting as a key tumor suppressor gene that is often mutated in colon cancer but has also been implicated in ovarian cancer development." (PMID 21390237, 2011). "APC is mutated in 80% of sporadic colon carcinomas by either allelic loss or mutations in the multi cluster region (MCR), and there appears to be an interdependence of the two hits." (PMID 21176237, 2010). "For example, mutations in the β-catenin/CTNNB1 gene have been reported in aggressive fibromatosis (also called desmoid tumor) and parathyroid tumors and mutations in the APC gene are often found in colon cancers." (PMID 20459685, 2010). "The majority of somatic APC mutations in colon cancers result in overexpression of a truncated protein that includes all of the M2-APC region and part of M3-APC." (PMID 20368985, 2010). "Constitutive active Wnt signaling either through mutations of β-catenin or loss of adenomatous polyposis coli (APC) function frequently leads to cancer, as particularly well understood for colon cancer." (PMID 20953359, 2010). "The loss of functional APC is associated with colon cancer and this is evident in mice with mutant APC: these APCmin mice develop multiple intestinal tumours." (PMID 27713339, 2010). "In animal studies, COX-2 mRNA and protein level in adenomatous tissue is three fold higher than normal mucosa of the same Min mouse bearing a mutation in the APC gene and markedly elevated in carcinogen-induced rat colonic tumours." (PMID 20346115, 2010). "Further experiments comparing topo IIα activity in colon cancer cell lines harboring various truncating APC mutations are needed to establish a direct link between topo IIα activity and aneuploidy." (PMID 20368985, 2010). "80% of colon cancers have APC mutations and 50-70% of breast, colon and lung cancers have EGFR and ErB3 mutations." (PMID 20828404, 2010). "Overexpression of SND1 in colon cancer cells caused down-regulation of APC and activation of the Wnt signaling pathway as a consequence, without altering APC mRNA levels." (PMID 20957089, 2010). "This possible connection in colon cancer between different types of APC mutations, cell cycle control gene expression, CIN and prognosis warrants further investigation." (PMID 21176237, 2010). "To test the significance of APC in phospho-β-catenin localisation at cell extensions, we examined P33/37/41-β-catenin in colon cancer cells containing either intact or mutated APC." (PMID 21152425, 2010). "Loss of normal APC function is known to be an early event in both familial and sporadic colon cancer pathogenesis, occurring at the pre-adenoma stage." (PMID 19822006, 2009).
colon carcinoma (continued). "Here we survey Groucho activity in six colon cancer cell lines that vary according to APC status and loss of β-catenin binding and nuclear localization motifs." (PMID 19460168, 2009). "Instead, the majority of colon cancers harbour truncating mutations in APC or stabilizing mutations in β-catenin." (PMID 19460168, 2009). "Secreted Frizzled-related protein-1 can also inhibit β-catenin/Tcf activity in colon cancer cells with mutations in APC that stabilise β-catenin." (PMID 19277043, 2009). "The most common mutations in colon cancer and derived cell lines result in truncating mutations of the APC protein." (PMID 19460168, 2009). "Conversely, DLD-1, SW480 and Colo320 colon cancer lines have high levels of nuclear APC; all of these lines have type I mutations that result in significantly truncated APC protein." (PMID 19460168, 2009). "We have recently reported that frizzled-7 (FZD7), 1 of 10 members of the FZD gene family, is predominantly expressed in colon cancer cells and is implicated in canonical Wnt signalling in colon cancer cells with APC or CTNNB1 mutations." (PMID 19773752, 2009). "For example, adenomatous polyposis coli (APC) mutations in hereditary colon cancer directly led to the identification of other genes involved in the more common sporadic and polygenic forms of colon cancer." (PMID 19479031, 2009). "Loss-of-function mutations inthe APC gene are common in human familial adenomatous polyposis and canbe found in sporadic colon cancers as well." (PMID 18784849, 2008). "A woman with a 3'APC mutation (c.5030_5031insAA) developed colon cancer at age 72 as the first manifestation of attenuated FAP." (PMID 19036155, 2008). "Low Tcf activity has been reported in about half of the colon cancer cell lines where it has been tested, despite the presence of confirmed mutations in either APC or β-catenin." (PMID 17020613, 2006). "Any success would also be relevant to prevention of nonhereditary cancer, which would be especially important for colon cancer since most cases involve somatic mutations in the APC gene." (PMID 16231982, 2005). "Patients harbouring a tumour with absent hMLH1 expression were older, more often women, more often had proximal colon tumours that showed poorer differentiation when compared to patients harbouring tumours with an APC and/or K-ras mutation." (PMID 16356174, 2005). "Gene mutations that are commonly observed in colon cancers including K-ras and APC are also observed in a proportion of ACF." (PMID 15928667, 2005). "Patients harbouring a tumour with absent hMLH1 expression were older, more often women, more often had proximal colon tumours that showed poorer differentiation when compared to patients who harboured a tumour with an APC and/or K-ras mutation." (PMID 16356174, 2005). "Moreover, P2X7 and A2A upraise in metastatic and APC-mutated colon carcinoma patients and in Apc-disrupted rats." (PMID 40759630, 2025). "IECs-specific knockdown of Ahr led to the expansion of clonogenic progenitor cells in mice with mutations in adenomatous polyposis coli (APC) and Kras genes (ApcS580/+; KrasG12D/+) and promoted cell growth in the gut epithelium to increase cecum and colon cancer in mice." (PMID 40765830, 2025). "Adenomatous polyposis coli (APC) mutations and chronic inflammation can each promote colon cancer." (PMID 40545113, 2025). "In addition, Lys‐des‐Arg9‐BK can effectively repair the epithelial mucosal barrier damage caused by colitis, maintain intestinal homeostasis, and reduce the incidence of colitis‐related colon cancer and APC‐deficient adenoma carcinoma by binding to B1R." (PMID 40859429, 2025).
colon carcinoma (continued). "In patients with sporadic colorectal cancer, the tumor suppressor adenomatous polyposis coli (APC) gene is mutated early to activate the canonical Wnt/β-catenin signaling pathway, whereas in patients with colitis-associated colon cancer, APC mutations occur late in cancer progression." (PMID 39068486, 2024). "Most KRAS-mutant colon cancers tend to occur in the context of APC mutation, suggesting that profound Wnt activation might be a key dependency for KRAS mutation." (PMID 38360902, 2024). "In addition, colon cancer cells with APC mutations have weakened kinetochore-microtubule interactions." (PMID 39021676, 2024). "Based on above findings, we hypothesized that APC mutations in human colon cancer tissues would upregulate the expression of eIF3a." (PMID 39413959, 2024). "In DMH-treated rats, up to 33% of colon tumors harbor APC mutations." (PMID 39339648, 2024). "As Bcl11b is a nuclear protein and activated the Wnt reporter in APC-mutated colon cancer cells, we hypothesized that it might work downstream of β-catenin." (PMID 39433900, 2024). "However, over-expressing the wild-type APC gene drastically reduced eIF3a expression at both protein and mRNA levels in human colon cancer HT29 and CaCo-2 cells, which are known to have mutated APC gene." (PMID 39413959, 2024). "Interestingly, no alterations were observed in protein expression in KM12SM cells after SHN3 silencing, likely because APC mutations in colon carcinomas prevent β-catenin degradation." (PMID 37963919, 2023). "Mutations in the GSK-3 phosphorylation site of β-catenin, which stabilize the protein and activate downstream signaling, also account for a substantial percentage of sporadic colon cancers that lack APC mutations and are the most common Wnt pathway mutation in HCC." (PMID 37759479, 2023). "We propose that APC c.3920T>A; p.Ile1307Lys may act as a pathogenic variant in this population, and may prove a useful marker for colon cancer risk in Arab populations." (PMID 37306523, 2023). "Adenomatous polyposis (APC) gene mutation is one of the inherited forms of human colon cancer." (PMID 37164974, 2023). "Such translocation and accumulation of β-catenin in the nucleus from cell membrane has been shown to be closely associated with the development or progression of colon tumors through mutations in the β-catenin or APC genes or activation of the Wnt/β-catenin signaling pathway." (PMID 35351212, 2022). "For example, a mutation in APC is linked to colon cancer, this mutation leads to unchecked expression of β-catenin and the cancer is due to APC mutation which in turn leads to sustained over expression of β-catenin overtime that mediates enhanced cell turnover." (PMID 35255110, 2022). "Most of the variants affected autosomal-dominant CPGs not previously linked to HB, since only one mutation was detected in a known gene of HB development (APC), in a familial context of relatives diagnosed with FAP/colon cancer which segregated with the APC mutation." (PMID 35495172, 2022).
colon carcinoma (continued). "CA decreases intracellular β-catenin levels and suppresses APC-mutated colon cancer cell growth." (PMID 34445346, 2021). "Mutation and inactivation of APC is regarded as essential to the initiation of colon cancer through loss of APC tumor suppressive functions, such as regulating the canonical Wnt signaling pathway to control cell proliferation and differentiation, cell adhesion, and cell migration." (PMID 34162944, 2021). "Adenomatous polyposis coli (APC) is known to be frequently mutated in human colon cancer." (PMID 34502304, 2021). "In the current study, we focused on β-catenin expression and transactivation since mutations in APC tumor suppressor genes are observed in 90% of colon cancer patients, and the end point of this mutation results in the activation of β-catenin transcriptional activity in human colon cancers." (PMID 34361052, 2021). "Mutations in APC occur in approximately 70%–80% of human colon tumors, which activate the Wnt/beta-catenin pathway to induce beta-catenin to form complexes with the TCF/LEF nucleus partner in the nucleus, subsequently regulating the expression of beta-catenin target genes." (PMID 34680448, 2021). "Besides, survival analyses showed APC mutation had adverse impact on immunotherapy while patients with BRAF mutation were more suitable for immunotherapy in colon cancer." (PMID 34211853, 2021). "Notably, mutations in either APC or CTNNB1 were also found in colon cancer, leading to increased activity of beta-catenin-Tcf signaling." (PMID 34488905, 2021). "It was reported that USP7 could activate Wnt signaling pathway and promote tumorigenesis by mediating β-catenin deubiquitination in adenomatous polyposis coli (APC) mutations from colon tumors." (PMID 34740372, 2021). "(vi) APC mutations are required for the maintenance of colon carcinomas." (PMID 33112876, 2020). "Colon cancer primarily increases through abnormal directions of the Wnt/β-catenin pathway, either activating mutations in β-catenin or disabling mutations in the β-catenin regulator, adenomatous polyposis coli (APC)." (PMID 32492917, 2020). "In cancers where canonical Wnt signalling is a key driver of the disease (eg through mutations in β-catenin or APC), such as colon cancer, ROR2 may play a major role in inhibiting the canonical pathway through binding to Wnt5a." (PMID 32807831, 2020). "APC is mutated in 61% of rectal cancers and in 48% of colon cancers." (PMID 32580435, 2020). "Mutated APC has been observed in early stage colon cancer and is correlated with clinical outcomes." (PMID 33254149, 2020). "Interestingly, the remaining cases (nearly 15%) of colon cancer, which lack APC mutations, carry genetic or epigenetic changes in some other components of the Wnt/β-Catenin signaling pathway (like the genes encoding Axin, β-Catenin, and sFRP)[60 ▶-63 ▶]." (PMID 32429632, 2020). "Besides colon cancer cells, inactivating mutations in APC or the Axin tumor suppressor proteins or activating mutations in β-catenin resulting in positive effects on T-cell factor (TCF)-regulated transcription have been described in several cancer types." (PMID 32375405, 2020). "Colon cancer cells harbouring a mutated APC gene are resistant to treatment of 5-FU." (PMID 32503256, 2020).
colon carcinoma (continued). "Moreover, the inactivation of RhoA resulted in larger and more numerous adenomas and decreased survival in an APC mutation-driven murine colon cancer model." (PMID 32244355, 2020). "The wingless-type MMTV integration site family (WNT) pathway, discovered as a key developmental signaling pathway, entered the cancer research scene in early 1990s with finding that APC (adenomatous polyposis coli) tumor suppressor gene mutations contribute to activation of WNT in colon cancer." (PMID 32545208, 2020). "In previous work, we demonstrated that a somatic colon cancer variant of pol β, K289M, misincorporates deoxynucleotides at significantly increased frequencies over wild-type pol β within a mutation hotspot that is present several times within the APC gene." (PMID 31732732, 2019). "Likewise, the intron 4 splice-donor site variant in the adenomatous polyposis coli (APC) gene causes skipping of exon 4, which can lead to colon cancer." (PMID 31779641, 2019). "Besides protecting against bone loss and beneficially affecting cholesterol metabolism, here we provide evidence in controlling the growth of adenomatous lesions, where mutations in APC form the initial oncogenic insult in 80% of all metastatic colon cancers." (PMID 30885958, 2019). "Besides, curcumin given orally to colon cancer mice carrying APC gene mutation (Min/+) increased the enterocyte apoptosis and decreased expression of β-catenin oncoproteins." (PMID 31108984, 2019). "The large majority of colon cancer patients carry inactivating APC mutations." (PMID 29652830, 2018). "The risk allele—in the APC gene (MIM: 611731)—is a well-studied founder variant in the Ashkenazi Jewish population that the NCCN has described as a moderate risk allele for colon cancer and for which it has issued screening guidelines for individuals who are heterozygous for this variant." (PMID 30487145, 2018). "Subsequently, APC was thought to promote destruction complex activity by preventing β-catenin dephosphorylation; however, the level of β-catenin phosphorylation remains high in multiple different colon cancer cell lines in which APC is inactivated by mutation." (PMID 29408853, 2018). "Inactivating APC pathogenic variants are almost exclusively found in colon tumors." (PMID 29124495, 2018). "One view suggests that this pathway is less involved in IBD-dependent carcinogenesis: this view is supported by the observation that APC loss is a less frequent event in IBD-associated colon cancer than in sporadic CRC and occurs late in the development of colitis-associated dysplasia and cancer." (PMID 29652830, 2018). "Furthermore, β-catenin, activated after Adenomatous polyposis coli (APC) mutation which occurs in the majority of colon cancers, interacts with and requires Tip60 for activity." (PMID 28717171, 2017). "Here, we tested the hypothesis that extracellular inhibitors of the Wnt pathway, although acting upstream of the APC mutation, can restore normal levels of pathway activity in colon cancer cells." (PMID 28708837, 2017). "APC is often affected by NMD-elicit mutations in colon cancer (COAD) and rectal cancer (READ)." (PMID 28649990, 2017). "APC is a target gene of four miRNAs that hsa-mir-22, hsa-mir-3065, hsa-mir-497 and hsa-mir-7-2 identified in our study, the mutation of APC can induce inherited syndromes familiar adenomatous polyposis which leads to a greater potential of colon cancer." (PMID 29513198, 2017). "The truncations of the APC protein lead to the loss of β-catenin and/or axin binding sites and prevent β-catenin degradation, resulting in abnormally high levels of cytoplasmic and nuclear β-catenin in colon tumor cells." (PMID 28769798, 2017).